OR7C2 (olfactory receptor family 7 subfamily C member 2)
Description:
Odorant receptor.
Synonyms: OR19-18; OR7C3; CIT-HSP-87M17
Tractability: Antibody: UniProt places it where antibodies can reach, with medium confidence; UniProt predicts a signal peptide or a membrane-spanning region; its Gene Ontology location is reachable by antibodies, with medium confidence.
Gene: Protein-coding gene on chromosome 19 (14,941,489 to 14,942,448, forward strand). Ensembl gene ENSG00000127529.
Subcellular location: Cell membrane
Pathways (Reactome):
Sensory Perception: Expression and translocation of olfactory receptors
Gene Ontology:
Molecular function: protein binding; olfactory receptor activity; G protein-coupled receptor activity; signaling receptor activity
Biological process: signal transduction; detection of chemical stimulus involved in sensory perception of smell; G protein-coupled receptor signaling pathway; sensory perception of chemical stimulus
Cellular component: plasma membrane; membrane
Genetic constraint (gnomAD): Loss-of-function variants: 0 observed, 0.38 expected, observed/expected ratio (o/e) 0, 90% interval 0 to 1.85. That is too few expected variants to judge how well the gene tolerates losing a copy. Missense variants: 374 observed, 406.8 expected, observed/expected ratio (o/e) 0.92, 90% interval 0.84 to 1. Synonymous variants: 160 observed, 166.8 expected, observed/expected ratio (o/e) 0.96, 90% interval 0.84 to 1.09.
Homologues: Orthologues: chimpanzee OR7C2 (98% identical), macaque OR7C2 (92% identical), rat Or7c70 (72% identical), mouse Or7c70 (72% identical). Paralogues in human: OR7C1 (78% identical), OR7D4 (67% identical), OR7A10 (65% identical), OR7A17 (64% identical), OR7A5 (64% identical), OR7D2 (62% identical), OR7E24 (61% identical), OR7G2 (61% identical), OR7G3 (61% identical), OR7G1 (59% identical), OR1S1 (54% identical), OR1E1 (54% identical), and 116 more.